HOXB7 (homeobox B7)
Description:
Sequence-specific transcription factor which is part of a developmental regulatory system that provides cells with specific positional identities on the anterior-posterior axis.
Synonyms: HOX2C; HHO.C1; HOX2; Hox-2.3
Tractability: PROTAC: ubiquitination databases record sites on it.
Gene: Protein-coding gene on chromosome 17 (48,607,232 to 48,633,572, reverse strand). Ensembl gene ENSG00000260027.
Subcellular location: Nucleus
Subcellular location (Human Protein Atlas): Nuclear bodies; Nucleoplasm; Cytosol
Gene Ontology:
Molecular function: DNA-binding transcription activator activity, RNA polymerase II-specific; protein binding; RNA polymerase II cis-regulatory region sequence-specific DNA binding; sequence-specific double-stranded DNA binding; DNA-binding transcription factor activity; DNA-binding transcription factor activity, RNA polymerase II-specific; DNA binding
Biological process: embryonic organ development; positive regulation of transcription by RNA polymerase II; anterior/posterior pattern specification; regulation of DNA-templated transcription; regulation of transcription by RNA polymerase II; positive regulation of branching involved in ureteric bud morphogenesis
Cellular component: nuclear body; nucleoplasm; chromatin; nucleus
Genetic constraint (gnomAD): Loss-of-function variants: 14 observed, 18.14 expected, observed/expected ratio (o/e) 0.77, 90% interval 0.51 to 1.21. The upper end of that interval is the gene's LOEUF score, 1.21, which puts it in group 5 of 6, group 1 being the genes least tolerant of losing a copy. Missense variants: 318 observed, 280.3 expected, observed/expected ratio (o/e) 1.13, 90% interval 1.03 to 1.25. Synonymous variants: 141 observed, 122.08 expected, observed/expected ratio (o/e) 1.15, 90% interval 1.01 to 1.33.
Homologues: Orthologues: chimpanzee HOXB7 (99% identical), macaque HOXB7 (97% identical), dog HOXB7 (96% identical), pig HOXB7 (96% identical), mouse Hoxb7 (94% identical), rat Hoxb7 (93% identical), zebrafish hoxb7a (60% identical). Paralogues in human: HOXA7 (59% identical), HOXB6 (43% identical), HOXA6 (42% identical), HOXB5 (40% identical), HOXA5 (40% identical), HOXC6 (40% identical), HOXB8 (38% identical), HOXC8 (38% identical), HOXD8 (36% identical), HOXC4 (36% identical), HOXD4 (35% identical), HOXB4 (34% identical), and 30 more.
Diseases named in the same sentence as HOXB7 in open-access papers:
HOXB7 is named in the same sentence as 102 diseases in open-access papers, as found by Europe PMC text mining. Sharing a sentence is not in itself a finding about the gene and the disease. The quoted sentences say what the papers report.
breast cancer (42 papers, 2007 to 2025). A primary or metastatic malignant neoplasm involving the breast. "HOXB7 was reported as a hallmark in the glioma, lung cancer, and breast cancer, and its role in SDC needs to be further elucidated." (PMID 36527158, 2022). "To date, HOXB7 has been implicated to be aberrantly expressed in several types of cancers, including breast cancer, gliomas, gastric cancer, esophageal squamous cell carcinoma, intrahepatic cholangiocarcinoma, and cervical cancer." (PMID 35087752, 2021). "For example, HOXB7 overexpression was reported in association with the clinical progression and poor outcome of patients with breast cancer." (PMID 34303375, 2021). "Previous studies have shown overexpression of HOXB7 to be closely associated with the clinical progression and poor prognosis of patients with breast cancer, oral squamous cell carcinomas, ovarian cancer, lung adenocarcinoma, and esophageal squamous cell cancer." (PMID 24641834, 2014). "Moreover, HOXB7 overexpression has been linked to macrophage recruitment and activation as well as to the stimulation of DNA double-stranded break repair, thereby improving breast cancer survival after irradiation." (PMID 41040515, 2025). "HOXB7 upregulation has been observed in hepatocellular carcinoma, oral squamous cell carcinoma, colorectal cancer, breast cancer, and intrahepatic cholangiocarcinoma." (PMID 41040515, 2025). "In breast cancer cells, overexpression of the estrogen receptor ERα inhibits HOXB7 expression, but the specific molecular mechanism has not been elucidated." (PMID 39706274, 2025). "In fact, a previous work of our group showed that HNP were able to deliver siRNA to breast cancer cells for a significant HOXB7 gene silence in vitro." (PMID 39458966, 2024). "The HOXB7 gene is known to be related to TMX resistance in positive hormone receptor molecular subtype breast cancer." (PMID 39458966, 2024). "In fact, by reducing HOXB7 gene expression, we expect to re-sensitize Luminal A breast cancer to TMX." (PMID 39458966, 2024). "TGF-β2 expression was upregulated in four MMTV-HoxB7/Her2 transgenic mouse tumour cell lines and two breast cancer cell lines after HOXB7 overexpression, whereas TGF-β2 expression was reduced in HoxB7-depleted cells." (PMID 38067167, 2023). "The introduction of HOXB7 strongly increased the tumorigenic properties of breast cancer cells SkBr3 (SkBr3/B7)." (PMID 37445737, 2023). "It has been showed that the overexpression of PBX2 increases the tumorigenic properties of SkBr3 breast cancer cell line when transfected with HoxB7." (PMID 36338974, 2022). "In breast cancer, HOXB7 has been reported as an oncogene because its upregulation appears to promote the expression of bFGF and induce the epithelial-mesenchymal transitions (EMT)." (PMID 34722321, 2021). "HOXB7 is a transcription factor previously related to poor outcome in breast cancer, affecting epidermal to mesenchymal transition or angiogenesis." (PMID 33741018, 2021). "The homeobox transcription factor, HOXB7, is upregulated in mammary carcinomas, and HOXB7 expression confers EMT-like phenotypical features in breast cancer cells." (PMID 33923319, 2021). "HOXB7 is overexpressed in all breast cancer (BC) cell lines studied, including in the MDA-MB-468, which is representative of the triple-negative molecular subtype." (PMID 34680970, 2021). "In some cases, higher expression levels of HOXB7 were found to correlate with poorer disease-free survival in ERα+ breast cancer patients on adjuvant tamoxifen therapy." (PMID 34680970, 2021). "Firstly, HOXB7 has been reported to be aberrantly expressed in various malignancies, such as oral cancer, lung cancer, breast cancer, gastric cancer, liver cancer and esophageal cancer." (PMID 34303375, 2021). "The altered expression of HOXB7, for example, was reported to promote breast cancer progression in specific subtypes." (PMID 34063128, 2021).
breast cancer (continued). "MEIS2, which belongs to the same family of HOXB7, has been also reported to be a master regulator in breast cancer." (PMID 33741018, 2021). "HOXB7 overexpression, for example, induces invasive and metastatic breast cancer by activating the TGFβ signalling pathway." (PMID 33375038, 2020). "This role has been demonstrated for HOXB7 which promotes EMT in breast cancer, and for HOXA10 whose silencing induces EMT in endometrial and lung cancer." (PMID 30974862, 2019). "HOXB7 has been reported to inhibit transgenic HER-2/Neu-induced mouse mammary tumor onset but promotes progression and lung metastasis of breast cancer." (PMID 30664713, 2019). "Homeobox B7 (HOXB7) has been reported to be aberrantly expressed in a variety of cancers, including melanoma, breast cancer, gastric cancer, liver cancer, colorectal cancer and esophageal cancer." (PMID 30664713, 2019). "Homeobox B7 (HOXB7), a member of homeobox gene family, has been shown to be involved in several cancers, including gastric, oral, pancreatic and breast cancer." (PMID 28646927, 2017). "Breast cancer cells overexpressing HOXB7 or HOXB13 show repression of the estrogen receptor leading to estrogen independence and resistance to tamoxifen." (PMID 27449292, 2016). "The overexpression of HOXB7 was showed to be related to poor prognosis in breast cancer, oral cancer, colorectal cancer, lung cancer and pancreatic adenocarcinoma." (PMID 26076456, 2015). "Exploring how HOXB7 expression is controlled in breast cancer cells, miR-196a was identified as an upstream controller of HOXB7 expression." (PMID 26697525, 2015). "In fact, the dysregulation of HOXB7 expression has been reported in a variety of tumors, including breast cancer, ovarian cancer, oral cancer, colorectal cancer, lung cancer, melanoma and pancreatic cancer." (PMID 26076456, 2015). "HOXB7 is a homeodomain containing transcription factor which plays a pivotal role in tamoxifen resistant breast cancer." (PMID 26697525, 2015). "Taken together, these studies on HOXB7 provide significant insights and knowledge of pathways critical to the development of tamoxifen resistant breast cancer." (PMID 26697525, 2015). "EGFR expression is upregulated by direct binding of HOXB7 to the EGFR promoter, while HOXB7 functions as a cofactor with ERα to cause overexpression of multiple ER-target genes, including HER2, in tamoxifen resistant breast cancer cells." (PMID 26697525, 2015). "In a breast cancer cell line (SkBr3), transduction of HOXB7 gene induces bFGF expression, increases growth rate and ability of cells to form colonies in semisolid medium." (PMID 24088503, 2013). "Our current study also demonstrated that VEGF was a downstream transcriptional target of HOXB7 in cervical cancer, which has also been reported for breast cancer, as well as multiple myeloma." (PMID 23861821, 2013). "Therefore, we used calcium phosphate hybrid nanoparticles (HNP) for the delivery of short interfering RNA molecule (siRNA) complementary to the HOXB7 gene and evaluated the RNA interference (RNAi) effects associated with TMX treatment in breast cancer in vivo." (PMID 39458966, 2024). "Furthermore, the Homeobox B7 protein (HoxB7) transcription factor, which is upregulated in breast cancer, drives the selective transcription of TGF-β2." (PMID 38675493, 2024). "HOXB7 is often overexpressed in breast cancer cells and found to relate to poor prognosis." (PMID 34680970, 2021). "In addition, we provide evidence that in Triple-Negative breast cancer cells, HOXB7 overexpression has the potential to promote less aggressive phenotypes." (PMID 34063128, 2021). "Results from a transcriptomic array indicated a series of newly described transcription factors including HOXB7, MEIS2, TCERG1, and DNAJC2, that were associated to poor outcome in HER2+ breast cancer subtype and downregulated by the MZ1-trastuzumab combination." (PMID 33741018, 2021).
breast cancer (continued). "In vitro studies using SkBr3 breast cancer cells provided the first evidence on how HOXB7 deregulation may affect breast cancer progression." (PMID 34680970, 2021). "Excessive HOXB7 inducing MET in breast cancer cells also interferes with DNA repair and tamoxifen." (PMID 34722321, 2021). "Interestingly, the induced overexpression of the mice counterpart (HOXB7) suggests a dual role in HER2/neu-induced mammary tumors: it delays tumor onset but promotes metastatic tumor progression." (PMID 34680970, 2021). "In addition, our results suggest that the HOXB7 role in breast cancer is strictly dependent on the cellular genetic background, especially regarding ER, EGFR, and HER2 expression, along with the modulation of the levels of this transcription factor." (PMID 34063128, 2021). "In addition, microarray analyses of dissected epithelial cells from bone metastasis revealed that HOXB7 overexpression was threefold higher than in primary breast carcinomas and eighteen-fold higher than in normal breasts." (PMID 34680970, 2021). "HOXB7 could directly activate the expression of basic fibroblast growth factor (bFGF) and promote growth of various tumors, such as breast cancer and melanoma." (PMID 26076456, 2015). "Previous microRNA expression profiles, confirmed by qRT-PCR analysis, had shown that HOXB7 retroviral transduction was sufficient to induce miR-221 and -222 up to three and five-fold, respectively, in a model of SkBr3 mammary carcinoma cell line (our unpublished results)." (PMID 23400877, 2013). "However, the specific targets affected by the deregulation of HOXB7 in breast cancer remain largely unknown in most molecular sub-types, such as triple-negative breast cancers (TNBC)." (PMID 34680970, 2021). "HOXB7 overexpression has also been associated with enhanced expression of several angiogenic growth factors including VEGF, Ang-2, and interleukin (IL)-8 in the breast cancer cell line SkBr3, indicating that HOXB7 is a critical factor for upstream pro-angiogenic genes." (PMID 33171691, 2020). "ChIP-seq assays have uncovered hundreds of HOXB7 chromatin binding sites in the breast cancer cell line, BT-474, with ectopic expression of HOXB7, thus providing a new avenue to a deep understanding of the function of HOXB7 in driving breast cancer progression and maybe multiple myeloma." (PMID 31013831, 2019). "In addition, HOXB7 facilitated the migration of breast cancer cells by inducing EMT." (PMID 28646927, 2017). "In Pharmacology, HOXB7 acts as an ER co-factor, regulating the role of numerous ER targets including HER2 in tamoxifen-resistant breast cancer." (PMID 34303375, 2021). "HOXB7, a member of the HOX gene family, has been shown as a strong oncogene in various human cancers, such as hepatocellular carcinoma, breast cancer, and osteosarcoma (28, –, 30)." (PMID 33782039, 2021). "Here we induced HOXB7 overexpression in MDA-MB-231 cells, a cellular model of the Triple-Negative breast cancer molecular subtype, and evaluated the phenotypic changes in cell viability, morphogenesis, migration, invasion, and colony formation." (PMID 34063128, 2021). "In another breast cancer cell line, MCF7, which represents the Luminal A molecular subtype, HOXB7 overexpression renders cells resistant to tamoxifen via cross-talk between receptor tyrosine kinases and ERα signaling." (PMID 34680970, 2021). "HOXB7 overexpression is associated with enhanced expression of angiogenic genes in the breast cancer cell line, SKBR3, indicating that HOXB7 is a critical factor upstream of pro-angiogenic genes." (PMID 31013831, 2019). "Among POL II bound homeobox genes is HOXB7 which has been reported to promote tumor progression, survival and metastasis once tumorigenesis has begun in HER2 overexpressing breast cancer." (PMID 25428913, 2015).
breast cancer (continued). "The entire mechanism involving FGF2, PBX1/PBX2, and HOXB7/HOXB8 in breast cancer tumorigenesis is not clear." (PMID 37445737, 2023). "HOXB7 induced EMT and promoted migration and invasion in breast cancer cells." (PMID 28646927, 2017). "We predicted that 6 genes including ANXA1 would be regulated by miR196a using 4 prediction softwares (TargetScan, MiRanda, Diana MicroT and PicTar), and confirmed the reduction of these genes (ANXA1, HOXA7, HOXB7, ING5, CDC73 and SMURF1) by miR-196a in breast cancer cells using qPCR analysis." (PMID 27105503, 2016). "For example, miR-196a has been studied for its oncogenic roles in glioblastoma, pancreatic adenocarcinoma, breast cancer, oesophageal adenocarcinoma, and colorectal cancer, and shown to target HOX family genes (HOXA7, HoxB7, HOXC8, HOXB8, HOXD8), ERG, HMGA2, ANXA1, S100A9, SPRR2C, KRTS." (PMID 24621885, 2014). "HOXB7 mRNA is overexpressed in breast and ovarian carcinomas and can promote metastasis by induction of epithelial-mesenchymal transition (EMT); HOXB13 overexpression correlates with tamoxifen resistance in breast cancer." (PMID 22844406, 2012). "Thus, this work aimed to apply these hybrid nanoparticles to deliver siRNA molecules to human breast cancer tumors in nude mice and assess the effects of HOXB7 gene silencing with and without TMX cotreatment in vivo." (PMID 39458966, 2024).
colorectal cancer (16 papers, 2014 to 2025). A primary or metastatic malignant neoplasm that affects the colon or rectum. "HOXB7 is also overexpressed in colorectal cancer, which can activate the PI3K/AKT and MAPK pathways." (PMID 40657360, 2025). "In colorectal cancer, circIFT80 promotes the development of colorectal cancer by entering exosomes, promotes DNA synthesis and inhibits apoptosis through the miRNA-1236-3p/HOXB7 axis." (PMID 34360530, 2021). "While, excessive overexpression of HOXB7 has highly confidential correlated with disease advancement and poor prognosis of esophageal squamous cell carcinoma and colorectal cancer." (PMID 34303375, 2021). "In colorectal cancer cells, HOXB7 is capable of inducing acceleration of G1-S transitions by activating PI3K/AKT and MAPK pathways, resulting in upregulation of p27Kip1 and cyclin D1." (PMID 31013831, 2019). "HOXB7 upregulation has been demonstrated in colorectal cancer and esophageal squamous cell carcinoma, and HOXB7 has been shown to indicate poor prognosis in individuals with both these diseases." (PMID 30664713, 2019). "HOXB7 expression is significantly upregulated in colorectal cancer, and expression of HOXB7 promotes the aggressiveness of cancer cells." (PMID 29367650, 2018). "A previous study reported that HOXB7 facilitated the proliferation of colorectal cancer cells by activating the PI3K/AKT pathway." (PMID 28646927, 2017). "The expression of HOXB7 is visibly related to the invasive and aggressive characteristics of human colorectal cancer (high Dukes stage, T stage, distant metastasis-positive tumors, and high proliferation index) and to poor survival of patients." (PMID 24641834, 2014). "Deregulation of HOXB7 expression in colorectal cancer predicted poor outcomes of patients." (PMID 34303375, 2021). "Moreover, another study suggested that in colorectal cancer, HOXB7 accelerated G0-G1 to S-phase transition concomitantly with upregulation of cyclin D1 and downregulation of p27Kip1 in tumor cells." (PMID 34303375, 2021). "In addition, increased metastases induced by mircoRNA-196b-5p in colorectal cancer is partially dependent on the regulation of HOXB7 and GALNT5 expression." (PMID 31013831, 2019). "We saw upregulation of hsa-miR-196a-5p and hsa-miR-196b-5p in colorectal carcinoma tissue as compared to normal colorectal mucosa; we subsequently saw a direct relationship with hsa-miR-196a-5p and HOXB7 and hsa-miR-196b-5p with HOXA10 in colonic carcinoma tissue." (PMID 27123865, 2016). "It was showed that PI3K/AKT and MAPK pathways were activated by HOXB7 in colorectal cancer, which may explain the accelerating G1–S transition induced by HOXB7." (PMID 26076456, 2015). "Interestingly, hsa-miR-196b-5p was also found to molecularly interact with HOXB7 and GALNT5 and inhibit their expression in colorectal cancer." (PMID 33333738, 2020).